LINC01215 (long independently transcribed non-coding RNA 1215)
Gene: Long non-coding RNA gene on chromosome 3 (108,097,871 to 108,138,610, forward strand). Ensembl gene ENSG00000271856.
Diseases named in the same sentence as LINC01215 in open-access papers:
LINC01215 is named in the same sentence as 7 diseases in open-access papers, as found by Europe PMC text mining. Sharing a sentence is not in itself a finding about the gene and the disease. The quoted sentences say what the papers report.
psoriasis (2 papers, 2021 to 2023). An autoimmune condition characterized by red, well-delineated plaques with silvery scales that are usually on the extensor surfaces and scalp. "We also identified the differential expression of LINC01215 and LINC1206 associated with the cell cycle pathway and psoriasis pathogenesis." (PMID 38003532, 2023). "Only LINC01215, LINC1206, LINC1269, SH3PXD2A-AS1, CERNA2 and PRKCQ-AS1 have known functions and pathways associated with psoriasis pathogenesis." (PMID 38003532, 2023). "We found that LINC01137, LINC01215, MAPKAPK5-AS1, TPT1-AS1, CARMN, CCDC18-AS1, EPB41L4A-AS, and LINC01214 may be potential diagnostic biomarkers for psoriasis." (PMID 33732554, 2021). "Our findings suggest that LINC01137, LINC01215, MAPKAPK5-AS1, TPT1-AS1, CARMN, CCDC18-AS1, EPB41L4A-AS, and LINC01214 may be potential diagnostic biomarkers for psoriasis and LINC01137, LINC01215, and LINC01214 may serve as predictive biomarkers for biologics response in psoriasis." (PMID 33732554, 2021). "We also corroborated the involvement of eight lncRNA genes involved in psoriasis as determined by previous studies, including EPHA1-AS1, CYP4Z2P, SNHG12, LINC01215, LINC1206, SH3PXD2A-AS1 and CERNA2." (PMID 38003532, 2023). "LINC01137, LINC01215, and LINC01214 may serve as predictive biomarkers for biological response in psoriasis." (PMID 33732554, 2021).
atopic dermatitis (1 paper, 2023). "LINC01215 upregulation, which is seen in our investigation, has been linked to general atopic dermatitis, another inflammatory skin disease." (PMID 38003532, 2023).
ovarian carcinoma (1 paper, 2023). A malignant neoplasm originating from the surface ovarian epithelium. "Furthermore, the downregulation of LINC01215 suppresses tumor growth, migration, and cell proliferation of ovarian cancer." (PMID 38162289, 2023).
respiratory syncytial virus infection (1 paper, 2021). "LINC01215 acted as a hub gene involved in the rehabilitation process through the T cell receptor signaling pathway in respiratory syncytial virus infection (Qian, Zhang & Wang, 2019)." (PMID 33732554, 2021).
tumor (3 papers, 2022 to 2024). "In addition, overexpression of LINC01215 resulted in significant acceleration of tumor growth, enlarged tumor volume, and increased metastasis observed in tumor xenograft models." (PMID 38725621, 2024).
LINC01215 also shares sentences with these, for which no sentence is quoted: infarction (1 paper); inflammatory skin disease (1).